CD27 (CD27 molecule)
Diseases named in the same sentence as CD27 in open-access papers (continued):
Sharing a sentence is not in itself a finding about the gene and the disease.
tumor (continued). "In the stroma, fibroblast activation markers were observed, as well as significantly higher VISTA and CD27 expression versus within the tumour." (PMID 37835491, 2023). "Targeting CD27 has also been shown to induce significant anti-tumor responses in several pre-clinical models." (PMID 37180119, 2023). "Altogether, these results support the general applicability of using agonistic anti-CD27 to enhance the effects of Treg-depleting mAb in different tumour models." (PMID 35288635, 2022). "To address a potential role of CD27 expression on Tregs in inhibiting anti-tumor immunity, we used a transplantable adenocarcinoma model to challenge mice with a conditional deficiency of CD27 in the Treg compartment." (PMID 34423375, 2022). "Currently, only PD1/PD-L1, CD47/SIRPα, TIM3/Galectin-9, and CD70/CD27 checkpoints have been shown to interact with each other to regulate tumor proliferation in pairs." (PMID 36358792, 2022). "As our data demonstrates that abrogation of Treg CD27 in combination with PD-1 signaling blockade affects CD8+ T cells numbers within the tumor, we next assessed effector function of intratumoral CD8+ T cells." (PMID 34423375, 2022). "Mouse models treated with CD27 agonists have also revealed these drugs’ preventive role in tumor formation or progression." (PMID 35659630, 2022). "Using a mixed bone marrow chimeric mouse model in which we can deplete regulatory T cells in a temporally controlled fashion, we show that Treg-expressed CD27 prevents the breakdown of peripheral tolerance and limits anti-tumor immunity." (PMID 34423375, 2022). "As a new generation of immune checkpoint inhibitors (ICIs), CD27 agonist antibodies are being tested as adjuvant therapy in phase I/II clinical trials, showing promising results for multiple tumor types." (PMID 36551208, 2022). "Within the primary-tumor-site subgroup, the subgroup analysis revealed that a CD27 increase was a protective factor for OS." (PMID 36458007, 2022). "Stromal expression of CD27 in primary tumor specimens, and NY-ESO.1 and B7-H3 expression in the nodal metastasis samples, was associated with improved OS." (PMID 35651606, 2022). "Ochsenbein and colleagues had previously demonstrated a reduced tumor growth and an increased apoptosis of tumor infiltrating Tregs in CD27 − / − mice." (PMID 34423375, 2022). "Within this seven-gene panel, CD27 is a target for immune checkpoint inhibitors (ICIs), and anti-CD27 mAb is being tested as an adjuvant immunotherapy in phase I/II clinical trials for multiple tumor types with promising results." (PMID 36499305, 2022). "In solid tumors, only expression of CD70 is present on the tumor cells which can facilitate immune evasion through CD27 expression in the tumor microenvironment." (PMID 34991665, 2022). "We show here, that the suppression of tumor growth resulting from ablation of CD27 in the Treg compartment, is strongly synergistically supported by blockade of PD-1." (PMID 34423375, 2022). "It was found that overexpression of CD70 on tumors can facilitate immune evasion through CD27 expression in tumor-infiltrating Tregs." (PMID 36239354, 2022). "Further, the expression level of immune checkpoint molecules (PDL1, CTLA4, LAG3, TIGIT, CD27, IDO1, ICOS) and tumor mutational burden (TMB) also showed significant differences between the two subtypes, indicating the clinical value of the two subtypes." (PMID 36568197, 2022). "High expression of the CD276 gene is thought to be associated with the development and metastasis of several cancers, and CD70 is involved in the survival of tumor cells and regulatory T cells through interaction with its ligand CD27." (PMID 35677427, 2022). "An exhaustion signature of 28 genes, including TIGIT, TNFRSF9/4-1BB, and CD27, was identified in exhausted T cells in melanoma tumours and was also found to be upregulated in high-exhaustion cells in most tumours." (PMID 36154923, 2022).
tumor (continued). "Upon the targeting of CD70-expressing tumor cells, CD27 expression on CAR-T cells was quickly downregulated, suggesting that chronic CD27 stimulation is potentially deleterious." (PMID 35053463, 2022). "In the CD4+T cell population analyzed, PRI revealed two bin-plot patterns (CD90/CD44/CD86 and CD90/CD44/CD27) and 20 bin plot features for threshold-independent classification of mice concerning ineffective and effective tumor treatment." (PMID 35592315, 2022). "CD27 + CD21lo/med B cells were enriched in resected tumors and were thought to be critical mediators of anti-tumor immunity." (PMID 34374937, 2022). "Previous studies have shown that direct CD27 ligation synergizes with PD-1/PDL1 blockade to unleash CD8+ T cell driven anti-tumor immunity." (PMID 34423375, 2022). "Our study showed increased FoxP3 expression and higher CD4+/CD8+ ratios in CD27+ tumor infiltrating lymphocytes surrounding CD70+ tumor cells in NSCLC patients." (PMID 34991665, 2022). "The P value for the interaction test was 0.026, suggesting a significant interaction between CD27 and the different primary tumor sites." (PMID 36458007, 2022). "NK cells also displayed a biased maturation profile toward CD27-CD11b+ NK cells as well as increased proportion of KLRG1+ cells in Bach2cKO mice compared to control mice after tumor challenge." (PMID 36190189, 2022). "Tumor control by CD27 Treg ablation and PD-1 blockade was completely abolished by depletion of CD8+ T cells." (PMID 34423375, 2022). "Agonistic CD27 monoclonal antibodies (mAb) have demonstrated impressive anti-tumour efficacy in multiple preclinical models but modest clinical responses." (PMID 35288635, 2022). "Blocking CD70/CD27 axis can abolish immune escape by T cell apoptosis, T cell exhaustion and Treg survival, therefore inhibiting tumor proliferation." (PMID 36588677, 2022). "Both naïve [CD19(+)CD27(−)] and memory [CD19(+)CD27(+)] B cells were detected in the peripheral blood of patients with CRC after tumor resection." (PMID 35185893, 2022). "CD27 can stimulate the anti-tumor effect of monoclonal antibodies, and the stimulation of CD27 on the T cells surface and NK cells can increase the release of chemokines." (PMID 34899848, 2021). "EE increases CD27+ immature and proinflammatory NK-cell proliferation in the bone marrow and blood of tumor-free mice." (PMID 34394087, 2021). "Both tumor and stroma regions of primary tumors had higher expression of immune activation and checkpoint markers—including Tim-3, CD27 and 4-1BB—compared to metastases located in all tissues." (PMID 34838031, 2021). "There was reported synergy between PD-1 blockade and CD27 stimulation for CD8+ T-cell driven anti-tumor immunity, indicating the therapeutic potential of CD27 in neoadjuvant PD-1 blockade in early-stage NSCLC." (PMID 35008645, 2021). "Together, these findings strongly suggest that CD27+CD28+ Temra cells reflect a unique ‘prequel’ of tumor-specific CD8+ T cell responses and can predict tumor prognosis and therapeutic efficacy of patients with cancer undergoing immunotherapy." (PMID 34593620, 2021). "As a new generation of immunotherapy target, CD27 is currently being tested in phase I/II clinical trials for multiple tumor types with promising results." (PMID 35008645, 2021). "Our combined analyses of immune cells in the blood and the tumor microenvironment suggests that signaling receptors e.g., CD27 and PD-1 can be coupled to common or distinct downstream TFs in different cell types and tissues." (PMID 34500467, 2021). "The elevated release of CD27 in the tumor supports a potential CD4+ T-cell help, as observed in the TC-1 model." (PMID 34885215, 2021). "CD20+ B cells are the most abundant in TLB, and mature CD40+ plasma cells, natural B cells, and CD27+ memory cells can also exert anti-tumor effects." (PMID 34235074, 2021).
tumor (continued). "The key requirement for this bifurcation is either timely upregulation or downregulation of the expression of CD27 and CD28 while re-expressing CD45RA, a hallmark of Temra, during tumor progression." (PMID 34593620, 2021). "Overall, our analysis evaluated B‐cell immunity in human CRC and revealed the attenuated antigen presentation and diminished antitumor immunity capacity of CD40+ and CD27+ B cells in tumor." (PMID 34185431, 2021). "In contrast, EE increases splenic CD27+ immature and proinflammatory NK-cell proliferation in tumor-bearing mice, which in turn have a lower tumor burden." (PMID 34394087, 2021). "Accordingly, we demonstrated that the relative proportion of CD27+CD28+ Temra inversely correlates with the number of CD8+ TILs and tumor mutation burden (TMB), known to affect the generation of neoantigens and the number of tumor-reactive CD8+ TILs." (PMID 34593620, 2021). "Previous preclinical studies using CD27-based CAR construct demonstrated efficient anti-tumor response and prolonged survival of CAR T cells in vivo by upregulating the anti-apoptotic protein Bcl-XL." (PMID 35117999, 2021). "This confirmed that higher expression of several known CTCL marker genes, including CD27, IL-32, CXCL13, BATF, and TIGIT28–32, was associated with spots with higher frequencies of tumor cells (see yellow highlighted genes)." (PMID 34795254, 2021). "In contrast, in TSCC, CD27-positive lymphocytes were observed in tumor nests and rather prominent in the fibrous stroma." (PMID 35145909, 2021). "Preliminary findings from a preclinical glioma model suggest that treatment of tumor bearing mice with vancomycin plus gentamicin decreased gut microbial diversity, decreased infiltration of CD27+CD11b+ cytotoxic NK cells and led to increased tumor burden." (PMID 33708214, 2021). "Other syngeneic tumor models in huCD27-Tg mice have shown that reductions in CD27-expressing Treg cells using varlilumab can also contribute to anti-tumor activity." (PMID 32451681, 2020). "CDX-527 was shown to mediate effector function against tumor cells overexpressing either CD27 or PD-L1." (PMID 32451681, 2020). "BCL1 expresses PD-L1 but not CD27 which would allow costimulation of T cells in the huCD27-Tg mice, enhancement of CD27 costimulation by crosslinking through PD-L1 in addition to FcR, and direct tumor killing through PD-L1." (PMID 32451681, 2020). "While the BsAb was designed to enhance T cell immunity CDX-527 binds to activating FcγRs and thereby can potentially mediate effector function such as ADCC against certain tumor cells overexpressing PD-L1 or CD27." (PMID 32451681, 2020). "In sum, our CD27-related findings bring attention to this molecule as a novel target allowing modulation of ILS-driven anti-tumor immune responses." (PMID 33113874, 2020). "CD70+ cancer cells communicate with CD27+ tumor infiltrating lymphocytes and induce their apoptosis." (PMID 33287223, 2020). "Tumor progression of the HCC patients was associated with dysfunction of the tumor-infiltrating NK cells, primarily the CD11b-CD27-NK subsets." (PMID 32117298, 2020). "Based on these results, we defined a tumor-induced plasmablast-like-enriched B cell population (TIPB) signature with the genes CD27, CD38, and PAX5." (PMID 31519915, 2019). "The agonistic CD27 mAb, varlimumab, promotes T-cell dependent tumor rejection in human CD27 transgenic mice, demonstrating that enhanced CD27 signaling can augment anti-tumor responses." (PMID 30788290, 2019). "In this retrospective study, we assessed the degree of CD70/CD27 expression across various tumour types while using one standardised and validated IHC assay." (PMID 31652572, 2019). "Co-expression of CD27 has also been described in several tumours of hematopoietic lineage, implicating a possible role for the CD70-CD27 axis in the regulation of tumour cell proliferation and survival." (PMID 31652572, 2019).
tumor (continued). "This overexpression facilitates immune suppression through CD27 signalling in the tumour microenvironment by enhanced survival of regulatory T cells, induction of T cell apoptosis, and skewing T cells towards a T cell exhausted phenotype." (PMID 31652572, 2019). "An ideal combination of CD27 agonism with DC vaccination would be in boosting immune responses to low frequency antigens (e.g., tumor antigens) prior to co-stimulation through receptors with delayed expression and memory responses such as ICOS or 4-1BB." (PMID 30788290, 2019). "Twenty-five MCL samples (38%) were positive for both CD70 and CD27, whereof 60% (15 samples) showed double positivity within ≥ 50% of tumour cells." (PMID 31652572, 2019). "Nonetheless, persistent signalling of CD27 can occur in the tumour micro-environment through its expression on tumour-infiltrating lymphocytes (TILs), particularly on immune suppressive Tregs." (PMID 31652572, 2019). "Immunotherapeutic strategies targeting stimulatory TNFRSF receptors to promote anti-tumor immune responses have tremendous potential and CD27 is an important candidate due to its unique role in both initiating as well as maintaining T cell responses." (PMID 30298117, 2018). "IL-17-producing (CD27—) gdT cells promote breast cancer metastasis by expanding and polarising the neutrophils to an immunosuppressive phenotype, which inhibits anti-tumour CD8+ T cells." (PMID 30405205, 2018). "In fact, it has been suggested that some tumors have developed a defense mechanism based on stimulation of CD27 shedding from tumor-infiltrating T cells." (PMID 30298117, 2018). "CD27 molecules expressed on the surface of NK cells can bind to CD70 molecules on the surface of tumor cells to transduce activation signals and enhance the expression and release of perforin and granzyme B and promote the killing activity of NK cells." (PMID 29643992, 2018). "These NKG2D CAR T cells can effectively target NKG2DLs expressing TNBC cells in vitro, and CD27 or 4-1BB costimulated CAR T cells can significantly reduce tumor growth in vivo." (PMID 29980239, 2018). "As such, there were barely any undifferentiated naïve (CD45RA+CD27+CD28+) T cells in the lung or tumor." (PMID 30505306, 2018). "Agonistic stimulation of CD27 is therefore a promising therapeutic concept in immuno-oncology intended to boost and sustain T cell driven anti-tumor responses." (PMID 30298117, 2018). "We have demonstrated that CD27 is expressed on LSCs from CML patients and that triggering of CD27 on LSCs in a murine CML model promotes tumor cell growth and disease progression by activating the Wnt pathway." (PMID 29868474, 2018). "Examination of NK cell populations revealed a significant decrease in the proportion of intermediately functionally mature NK cells populations (CD27+CD11b−) in ranitidine-treated tumor-bearing mice compared with untreated tumor-bearing controls." (PMID 30158936, 2018). "By neutralizing CD70–CD27 interactions it deprives cell growth signaling in tumor cells while inhibiting the activation and proliferation of CD27-positive Tregs." (PMID 29387053, 2017). "Especially the higher expression of CD27, which has been linked to better outcome of ACT, supports a beneficial effect of Ipilimumab before harvest and expansion of tumour-infiltrating lymphocytes." (PMID 28423678, 2017). "Anti-gp75 and anti-CD27 individually had some activity in reducing tumor burden but the combination was superior." (PMID 29198913, 2017). "Our data demonstrate a way in which an immunostimulatory mAb, anti-CD27, can be used to augment the activity of a direct tumor-targeting mAb (anti-CD20) to elicit experimental cures." (PMID 29198913, 2017). "Altogether, this and published data suggest that anti-CD27’s anti-tumor effect is in part mediated by CD8+ T cells." (PMID 29198913, 2017). "In a B16cOVA model of anti-CD27 therapy, NK cells were shown to be essential in early tumor control but dispensable when tumor engraftment was established." (PMID 29198913, 2017).
tumor (continued). "test anti-tumor efficacy of immunomodulatory antibodies combined with anti-CD20 and find that anti-CD27/CD20 has a strong benefit in several tumor models." (PMID 29198913, 2017). "In the Eμ-TCL1 model, therapy provided by either anti-CD20 or anti-CD27 alone was minimal, yet the combination delivered efficient tumor depletion, leading to experimental cures." (PMID 29198913, 2017). "The upregulation of Ifng and Cxcl9 by anti-CD27, and combination therapy, indicate that these treatments polarize the macrophages toward an anti-tumor phenotype." (PMID 29198913, 2017). "IL-15 provided similar performance in stimulating CART cell expansion and tumor-lysis functions in vitro than IL-2, but induced a less differentiated phenotype, with higher CD27 and CD28 expression." (PMID 27409425, 2016). "Conversely, it has also been reported that CD27 signaling can increase survival of Tregs in vivo and thereby promote tumor progression." (PMID 27656185, 2016). "Based on the distinctive HCLc immunophenotype, CD19+CD11c+CD103+CD27- tumour cells were purified by flow cytometry and matched CD3+CD19- germline T cells flow-sorted from splenocytes, to ~97% and ~98% purity respectively." (PMID 26871591, 2016). "Forced expression of CD70 in a transgenic mouse model provides protection against an otherwise lethal challenge of tumor cells by constitutive activation of the CD27 pathway." (PMID 26500773, 2015). "On the contrary, co-culture of CD70+ tumor cells and CD27+ immune cells was shown to inhibit alloreactive T cell proliferation and induce T cell apoptosis." (PMID 25792975, 2015). "IL-2 either as a monotherapy or in combination with CTLA-4 blockade increased the proportion of less fully differentiated (CD27-CD11b-) NK cells as compared with the exhausted (CD11b+) NK cells within the tumor observed with CTLA-4 blockade alone." (PMID 25992289, 2015). "For example, overexpression of CD70 by tumor cells has been shown to promote T cell dysfunction or apoptosis through CD27 signaling in vitro." (PMID 26500773, 2015). "In spite of this, in most studies, biological effects of CD70 have been demonstrated to be mediated by interactions of CD70 with its receptor CD27, which can have a dual role in regulating anti-tumor adaptive immune responses." (PMID 25792975, 2015). "One possible approach to treating patients with high tumor PD-L1 expression and associated low CD8:Foxp3 T-cell ratios is the addition of immune-stimulatory molecules, such as agonists of CD27, GITR, 4-1BB, OX40 and others." (PMID 26317902, 2015). "Analyses ex vivo revealed CD25 expression in the CD27+/CD11b− subset suggesting that tumor-induced activation in vivo is restricted to early NK cells." (PMID 25101668, 2014). "IgD+CD27− memory B cells were decreased from 23.4% in tumor tissue to 9.9% among CD19+CD20+ B cells in colorectal liver metastases." (PMID 25026291, 2014). "Bone marrow from WM patients contains elevated numbers of mast cells, which use CD70 (a ligand for the TNF-receptor superfamily member, CD27) on the cell surface to bind soluble CD27 (sCD27) secreted by tumor cells." (PMID 24106612, 2013). "Although the CD70/CD27 axis has prominent immunostimulatory activity in de novo induced immune responses, its role in the established tumor micro-environment appears paradoxically opposite, with the expansion and prolonged survival of Tregs." (PMID 23840967, 2013). "Yet, REM has been shown to greatly reduce CD28 and CD27 expression of the expanded TIL, and this is associated with reduced persistence and subsequent limited anti-tumor activity of the infused TIL." (PMID 23402380, 2013). "Correspondingly, agonistic triggering of CD27-signaling ensured generation of a tumor-specific T-cell response and protected against lymphoma, melanoma, and fibrosarcoma tumor growth upon i.v. or s.c. tumor challenge." (PMID 23840967, 2013).